RETN (resistin)
Diseases named in the same sentence as RETN in open-access papers (continued):
Sharing a sentence is not in itself a finding about the gene and the disease.
Obesity (continued). "Numerous studies have reported that circulating resistin levels are increased in human obesity and diabetes." (PMID 15578112, 2004). "Inflammatory endotoxin induced resistin in primary human macrophages via a cascade involving the secretion of inflammatory cytokines that circulate at increased levels in individuals with obesity." (PMID 15578112, 2004). "Some studies have reported that elevated serum resistin levels are associated with obesity, IR, and T2DM, while other studies have not confirmed these findings." (PMID 41562846, 2026). "Currently, both obesity and type 2 diabetes mellitus (T2DM) and cardiovascular diseases (CVD) have been recognized as chronic inflammatory diseases that are most likely linked to the action of cytokines and adipokines, including resistin." (PMID 40491594, 2025). "Therefore, the present study aimed to evaluate the influence of resistin on the modulation of functional activity in colostrum and blood phagocytes from mothers with overweight and obesity." (PMID 41301907, 2025). "As obesity progresses, the adipokine secretion profile becomes imbalanced, with increases in pro-inflammatory molecules such as resistin, tumor necrosis factor-alpha (TNF-α) and interleukin-6 (IL-6) among others and decreases in protective molecules like adiponectin, omentina-1, etc.." (PMID 41155642, 2025). "First, obesity is associated with a state of chronic low-grade systemic inflammation, characterized by elevated levels of pro-inflammatory cytokines, including tumor necrosis factor-alpha (TNF-α), interleukin-6 (IL-6), C-reactive protein (CRP), and resistin." (PMID 40426647, 2025). "Sex-specific effects must also be integrated: postmenopausal women with obesity may be particularly vulnerable due to adipose and inflammatory shifts affecting leptin and resistin." (PMID 41155642, 2025). "ROC analysis indicated that sdLDL (cutoff: 18.55 mg/dl) and resistin (cutoff: 750 pg/mL) could serve as prognostic markers for overweight and obesity." (PMID 41315571, 2025). "However, multiple studies in different populations have reported contradictory results when attempting to correlate serum resistin levels with obesity, IR, and T2D." (PMID 40283140, 2025). "Consequently, the role of resistin in obesity remains controversial, and we faced challenges interpreting our resistin findings within our study's limitations." (PMID 41417360, 2025). "Therefore, in obesity, high levels of resistin are related to inflammation, changes in steroidogenic molecular pathways, reduced testosterone levels, and failures in spermatogenesis." (PMID 40195898, 2025). "Further supporting this, SHBG overexpression in transgenic mice protects against high-fat (with carbohydrate) diet (HFD)-induced obesity and insulin resistance, improving glucose tolerance, lowering insulin levels, and attenuating increases in leptin and resistin levels." (PMID 41586225, 2025). "Elevated circulating resistin levels observed in obesity and type 2 diabetes mellitus contribute to insulin resistance through inhibition of adenosine monophosphate kinase (AMPK) activity in hepatic and skeletal muscle tissues, thereby disrupting insulin signaling pathways." (PMID 41347124, 2025). "Alterations in adipokines, such as decreased levels of adiponectin and increased levels of leptin, nicotinamide phosphoribosyltransferase (NAMPT)/Visfatin, and/or resistin, trigger abnormalities in MSC functions that promote obesity-associated illnesses and alter the response to MSC therapy." (PMID 40893809, 2025). "Chronic low-grade inflammation, characteristic of obesity, may attenuate the beneficial immunostimulatory effects of resistin, leading to a less effective immune response in the colostrum environment." (PMID 41301907, 2025). "In the obesity and diabetes groups, the levels of pro-inflammatory cytokines such as resistin, leptin, IL-6, and TNF-α were high, which might have expanded the mass of dysfunctional adipose tissue." (PMID 40095937, 2025).
Obesity (continued). "Furthermore, several hormones produced by adipose tissue, including leptin, adiponectin and resistin, are dysregulated in obesity, further contributing to impaired bone health." (PMID 40468942, 2025). "Obesity-driven inflammation, particularly via elevated resistin, chemerin, and leukotriene B4, may further amplify immune dysregulation and keratinocyte hyperproliferation, exacerbating HS symptoms." (PMID 40778338, 2025). "Although biomarkers such as 8-OHdG, IL-8, resistin, TNFR1, PTX-3, and sICAM-1 are closely associated with MUO and metabolic disorders, they have not yet been established as primary diagnostic biomarkers for obesity-tests in clinical practice." (PMID 40153192, 2025). "However, its concentrations fall in obesity, while leptin, resistin, and visfatin rise, driving NF-κB and JNK activation in macrophages and parenchymal cells, thereby amplifying systemic IR." (PMID 41463398, 2025). "Obesity also affects the metabolic and secretory functions of many tissues, which may raise serum resistin levels." (PMID 41315571, 2025). "In obesity, the white adipose tissue that accumulates around the organs acts as a metabolically active, endocrine organ by secreting adipocytokines such as leptin, adiponectin, and resistin, and inflammatory cytokines." (PMID 40104308, 2025). "Resistin expression was increased in participants with obesity, supporting inflammation." (PMID 40095937, 2025). "Serum resistin levels were notably increased in mouse models of genetic and diet‐induced obesity." (PMID 40195898, 2025). "Several others, 8-OHdG, Ca2+, IL-6, IL-8, resistin, TNF-α, and AEA, have been identified as predictors, as they have previously been associated with an increased risk of developing obesity-related conditions such as insulin resistance, metabolic syndrome, or cardiovascular disease." (PMID 40153192, 2025). "In previous studies, the relationship between obesity, resistin, and OA was investigated." (PMID 40104308, 2025). "English-language publications were included by searching the database - PubMed, ScienceDirect, EMBASE, using the terms - adolescent girls, PCOS, adipokines, leptin, adiponectin, resistin, apelin, vaspin, visfatin, ghrelin, omentin, obesity, insulin resistance, metabolic syndrome." (PMID 40491594, 2025). "In addition, increased plasma levels of resistin in obesity suggest that it is a potential mediator for obesity and inflammation-related OA." (PMID 40104308, 2025). "Thus far, studies on resistin have mainly focused on the correlation between overweight/obesity and its serum levels." (PMID 40507778, 2025). "Obesity contributes to a pro-inflammatory state that exacerbates psoriasis by secreting adipokines, such as leptin and resistin, which stimulate Th17 and Th1 cells, thereby increasing Il-17 and TNF-a cytokines, key factors involved in the pathogenesis of psoriasis." (PMID 40003621, 2025). "Hence, obesity alone and type 2 diabetes with obesity were significantly associated with TNF-α, IL-6, leptin, adiponectin, resistin, and ALR even after adjusting for sex (Model 2) or age (Model 3)." (PMID 40095937, 2025). "In addition, it has been shown that the serum level of resistin is elevated in obesity induced by a high-fat diet and in murine genetic models of disease." (PMID 38542187, 2024). "The expression of leptin and resistin is increased in obesity." (PMID 38767687, 2024). "In obesity, high resistin levels directly inhibit insulin-induced glucose uptake in adipocytes." (PMID 39335642, 2024). "In addition, we showed that apelin-12, vaspin and resistin correlated with indices of obesity, glucose and lipid metabolism." (PMID 39519480, 2024). "Third, obesity might lead to diabetes mellitus and depression through reduced adiponectin and increased leptin and resistin, indicating the importance of weight control." (PMID 37927197, 2024).
Obesity (continued). "This could be due to better controlling for confounding factors such as obesity and hyperlipidemia in more recent studies, however, the advancements in measuring resistin levels should also be taken into consideration." (PMID 38486190, 2024). "The opposing effects of adiponectin and resistin suggest that their interaction may shape the metabolic profile of obese individuals and contribute to obesity-related complications." (PMID 39596980, 2024). "Interestingly, NORM3 also reduced resistin, a pro‐inflammatory adipokine that links obesity to diabetes." (PMID 39474783, 2024). "Increasing numbers of M1 macrophages as well as activated adipocytes present in inflamed fat tissue produce TNF-α, IL-6 and other inflammatory mediators including leptin and resistin that promote the occurrence of cardio-metabolic syndrome and hypertension in obesity." (PMID 38541059, 2024). "This suggests that resistin may influence cancer development and progression by linking obesity to an increased inflammatory state, thus contributing to tumor development." (PMID 39184804, 2024). "IR, obesity, and NAFLD are all associated with alterations in circulating resistin levels." (PMID 39045929, 2024). "Obesity might lead to diabetes mellitus and depression through reduced adiponectin and increased leptin and resistin." (PMID 37927197, 2024). "However, obesity and the role of adiponectin, resistin and visfatin in insulin resistance occurrence have been demonstrated." (PMID 39273337, 2024). "The excess visceral adiposity, typical of obesity, is responsible for increasing the number of molecules that induce cancer pathogenesis, such as leptin, resistin, and other adipokines, in addition to pro-inflammatory cytokines such as IL-1, IL-6, IL -8, and TNF-α, elevating the risk of neoplasms." (PMID 39042663, 2024). "Resistin is an important adipokine which might also function as a link between obesity and degenerative musculoskeletal diseases." (PMID 39658574, 2024). "In obesity, an increase in the serum resistin concentration is observed." (PMID 38794651, 2024). "Taken together, our findings suggest that apelin-12, vaspin and resistin may be used as biomarkers in children and adolescents with overweight and obesity." (PMID 39519480, 2024). "Visceral fat produces a large amount of adipokines, which are mainly pro-inflammatory elements; in such a way that in obesity there is a decrease in anti-inflammatory adipokines (adiponectin), whereas there is an increase in pro-inflammatory ones such as resistin." (PMID 39125315, 2024). "For example, resistin has been demonstrated to enhance sympathetic activity in the skeletal muscle vasculature and kidneys, hence contributing to the elevated blood pressure and cardiovascular problems observed in individuals with obesity and diabetes." (PMID 39335642, 2024). "This points to resistin as a potential mediator between obesity and diabetes." (PMID 37239098, 2023). "Early evidence demonstrates that exercise can lower resistin levels in animal models of obesity." (PMID 36829858, 2023). "Adiponectin and resistin modulate pro-inflammatory environment in obesity." (PMID 37149591, 2023). "Baseline results of pro-inflammatory biomarkers, including serum interleukin (IL)-6, serum and gingival crevicular fluid (GCF), tumor necrosis factor (TNF)-a, serum C-reactive protein (CRP)/hs-CRP, and serum and GCF resistin, were higher in obesity subjects than in normal weight subjects." (PMID 37798684, 2023). "Obesity increases the concentration of leptin and resistin in the serum of pregnant women, which hypothetically may be caused by the increased volume of adipose tissue." (PMID 37432262, 2023). "However, in humans, the link between increased resistin levels and obesity/IR remains under debate and needs more epidemiological studies." (PMID 37283763, 2023).
Obesity (continued). "Furthermore, in obesity, oxidative stress, inflammation, and excessive production of certain adipokines such as resistin, increase insulin resistance." (PMID 36935499, 2023). "Based on data from animal studies or other clinical applications in addition to obesity, adipokines including adiponectin, vaspin, resistin, chemerin, visfatin, bone morphogenetic protein 7 (BMP-7) and tumor necrosis factor alpha (TNF-α) provide potential for human clinical application." (PMID 37239098, 2023). "A meta-analysis has shown that obesity can alter serum levels of pro-inflammatory mediators (i.e., IL-6, CRP, TNF-a, resistin and leptin) in patients with periodontitis, while periodontitis can alter the levels of these mediators in patients with obesity, aggravating the inflammatory profile." (PMID 37798684, 2023). "Moreover, based on the GCF and serum levels of resistin at baseline and the distal follow-up, it was found that obese patients had a higher expression of resistin, indicating an obesity-dominant higher level of pro-inflammatory expression." (PMID 37798684, 2023). "In obesity, upregulated resistin in adipose tissue inhibits endothelial nitric oxide synthase (eNOS) activity by increasing the expression of phosphatase and tensin homolog deleted on chromosome 10 (PTEN), but some protein hormones, such as adiponectin, are downregulated." (PMID 37054724, 2023). "It was found that SCFAs could modulate adiponectin and resistin gene expression through DNA methylation and may correct aberrant expressions of adiponectin and resistin by epigenetic regulation that might be helpful for obesity prevention." (PMID 38136564, 2023). "Additionally, factors related to adipose tissue, including resistin, peroxisome proliferator-activated receptor gamma, and peptide YY, are believed to participate in the detrimental influence of obesity on bone health." (PMID 37571429, 2023). "In this respect, concentrations of resistin and chemerin have already presented positive correlations with IR, circulating lipids or blood pressure pointed to relevant therapeutic treatment considerations for lowering circulating levels in obesity." (PMID 37239098, 2023). "However, it has been clearly shown that human adipose tissue-resident macrophages secrete resistin when chronic low-grade inflammation is present, such as in obesity and T2D." (PMID 37391843, 2023). "Moreover, several inflammatory substances released from adipocytes, such as resistin have been suggested to contribute toward the adverse effects of obesity on the heart by promoting myocardial hypertrophy and dysfunction." (PMID 37660205, 2023). "This initial characterization of resistin led to the hypothesis that it might serve as a pivotal link between obesity and diabetes, largely based on preliminary evidence suggesting that resistin can inhibit insulin activity in rodent models." (PMID 37761031, 2023). "Lp-PLA2 and resistin, mainly expressed by macrophages, are both coincidentally involved in some immune-related or lipid-related diseases, such as rheumatoid arthritis, atherosclerosis, obesity, and diabetes." (PMID 35433542, 2022). "Scientists have considered resistin to link obesity, especially visceral obesity, and diabetes." (PMID 36514764, 2022). "Obesity results in the increased secretion not only of TNF but also of resistin, IL1β and IL6." (PMID 36233290, 2022). "Moreover, KSK-74 significantly compensated for metabolic disturbances that accompany obesity, such as an increase in plasma triglyceride, resistin, and leptin levels; improved glucose tolerance; and protected experimental animals against adipocyte hypertrophy." (PMID 35806019, 2022). "Thus, this study aimed to determine the functional activity of macrophages present in the breast milk and colostrum of diabetic mothers with obesity and the effects of resistin on these cells." (PMID 36289594, 2022).
Obesity (continued). "Although the role of resistin in obesity and insulin resistance in humans is still highly debated, it has been found that resistin levels are higher in obese subjects than control subjects and significantly correlated with high adiposity and low insulin sensitivity." (PMID 35628332, 2022). "In addition, the proteins CCL25, GRIA4, HBEGF, NPPA and RETN, which are affected by RNAm-SNPs, have been reported to be related to obesity." (PMID 35879730, 2022). "Inflammatory processes linked to obesity occur in both vascular and non-vascular tissues, and endothelial cells are activated by the vasoactive chemicals secreted by adipocytes, such as resistin and leptin." (PMID 36299943, 2022). "DIO and genetic models of obesity reported increased leptin and resistin levels." (PMID 36135388, 2022). "Serum resistin levels are elevated in human obesity, insulin resistance, and T2D." (PMID 35406450, 2022). "Furthermore, several studies have found significantly low levels of resistin mRNA in the adipose tissue in various obese mouse models, such as db/db or high-fat diet–induced obesity, as well as in rat models with IR." (PMID 35213996, 2022). "In humans, resistin lies on chromosome 19p13.3, a region that has not been linked with susceptibility to obesity." (PMID 35114975, 2022). "The function and regulation of resistin may differ from the physiological state when compared with organisms affected by obesity and diabetes, since different direct and indirect regulatory mechanisms of resistin vary in experimental models." (PMID 36262532, 2022). "In this work, the resistin was higher in the colostrum of diabetic mothers with obesity." (PMID 36289594, 2022). "Among these, leptin, visfatin, and resistin have a pro-inflammatory role decreasing the insulin sensitivity and inducing the development of chronic complications; on the contrary, adiponectin shows anti-inflammatory properties in the context of obesity." (PMID 36386923, 2022). "Both drugs have proven to be effective in reducing inflammation through various pathways: they reduced CRP levels in patients with obesity, while colchicine was also effective in reducing IL‐6, IL‐16, resistin, complement proteins C5a and C9, and the activity of the COX‐2 enzyme." (PMID 35837843, 2022). "This suggests that human resistin acts similarly to murine resistin and could play an important role in the early onset and progression of obesity and insulin resistance." (PMID 35909571, 2022). "Interestingly, high resistin levels are not only present in patients with obesity-influenced cancers, but also in patients with obesity-independent cancer." (PMID 36291097, 2022). "Although it is known that the adipokines, resistin, and leptin might inhibit the formation of adipose tissue, further research is necessary to define its protective effect against obesity and insulin resistance in breastfed infants." (PMID 35225882, 2022). "Taken together, these data suggest that chitoglucan may be helpful in the prevention of diet-induced obesity and metabolic syndrome via regulation of resistin expression." (PMID 36612600, 2022). "And resistin can promote fat cell proliferation which facilitates obesity." (PMID 35418966, 2022). "Obesity results in inflammation, oxidative stress; abnormal lipid metabolism; the activation of the renin angiotensin–aldosterone system; and insulin resistance by producing adiponectin, leptin, and resistin, leading to renal function deterioration." (PMID 35628912, 2022). "Cats with obesity have higher resistin mRNA expression in adipose tissue compared to lean cats." (PMID 36248900, 2022). "In addition, human resistin is among the inflammatory regulators that act on macrophages, indicating that resistin plays a role in insulin resistance, obesity, and diabetes." (PMID 36289594, 2022). "In studies of subjects with obesity, high resistin concentrations correlate with weight and BMI." (PMID 35679338, 2022).